TSLP (thymic stromal lymphopoietin)
Diseases named in the same sentence as TSLP in open-access papers (continued):
Sharing a sentence is not in itself a finding about the gene and the disease.
Airway obstruction (9 papers, 2016 to 2024). Obstruction of conducting airways of the lung. "We believe our study may help to understand the role of TSLP, IL-33, and IL-17A in a positive feedback loop between the airway epithelium and inflammatory cells infiltrating the airways in obstructive lung diseases." (PMID 32842623, 2020). "However, a significant correlation between plasma TSLP and airway obstruction, as well as airflow reversibility, was indeed displayed in our results." (PMID 29580282, 2018). "Given that RSV induces a TSLP-dependent, IL-13–producing ILC2 response in mice and that IL-13 promotes airway obstruction, it is intriguing to consider the therapeutic potential of an anti-TSLP mAb for treating severe RSV infection." (PMID 27156176, 2016). "However, to our best knowledge, there have been no studies on the simultaneous assessment of periostin and TSLP levels and their potential link with the Th2 immune response in patients with these two obstructive lung diseases." (PMID 33203095, 2020).
lung carcinoma (9 papers, 2016 to 2025). "In the same study, it was demonstrated that macrophages purified from macroscopically normal lung parenchyma of patients with lung cancer constitutively express TSLP, TSLPR, and IL-7Rα." (PMID 40873585, 2025). "The authors suggested that in this experimental model of lung carcinogenesis, TSLP inhibits the early stages of lung cancer development." (PMID 40873585, 2025). "TSLP drove a significant CD4+ T cell response to block lung cancer progression from atypical alveolar hyperplasia to adenocarcinoma." (PMID 35565302, 2022). "Herein, we demonstrate that systemic TSLP induction suppressed spontaneous lung cancer development in KrasG12D mice." (PMID 35565302, 2022). "Herein, we demonstrate the potential of immunotherapy against lung cancer by examining the impact of Thymic Stromal Lymphopoietin (TSLP) cytokine induction on early lung cancer development." (PMID 35565302, 2022). "Our findings suggest that TSLP can be used in the early stages of lung cancer development to trigger a lasting immunity in the tissue and prevent the development of advanced disease." (PMID 35565302, 2022). "TSLP induction suppresses the development of invasive lung tumors in a mouse model of spontaneous lung cancer." (PMID 35565302, 2022). "The concentration of immunoreative total TSLP protein was higher in intratumoral lung cancer compared to peritumoral tissue." (PMID 34440780, 2021). "Peripheral blood monocytes and MDMs show some similarities with HLMs purified from lung cancer with respect to the TSLP system." (PMID 34440780, 2021). "TSLP was overexpressed intratumorally compared to peritumoral lung cancer tissue and benign lesions." (PMID 34440780, 2021). "A tumor-promoting function for TSLP was described in lung cancer, where TSLP expression in the tumor tissue was higher compared to the normal counterpart." (PMID 33042121, 2020). "Similar effects of chitin and Car/Thy on IL-25, IL-33, and TSLP were seen with H292 human lung mucoepidermoid carcinoma cells and A549 human lung carcinoma cells." (PMID 27463381, 2016). "Furthermore, these results provide the first demonstration that the molecular expression of the two isoforms of TSLP is differentially expressed at peri- and intratumoral levels in human lung cancer." (PMID 40873585, 2025). "In conclusion, TSLP released by lung macrophages can play a role in the autocrine circuit that could favor lung cancer progression." (PMID 40873585, 2025). "TSLP was overexpressed in intratumoral lung cancer and correlated with Foxp3+ Tregs." (PMID 40873585, 2025). "In addition, understanding the role of TSLP signaling to innate immune cells and Kras mutant tumor cells in regulating lung cancer development is an important area for future investigation." (PMID 35565302, 2022). "On the other hand, TSLP induction is capable of driving inflammatory Th2 cell activation, which blocks carcinogenesis by inducing terminal differentiation in a spontaneous breast and lung cancer models." (PMID 36467403, 2022). "Our results indicate that TSLP induction can generate a strong, long-lasting cancer suppressive immune response in the lung and provide a potential therapeutic approach for the prevention and treatment of lung cancer." (PMID 35565302, 2022). "TSLP protein and TSLP isoforms are found in intratumoral and peritumoral human lung cancer." (PMID 34440780, 2021). "We also examined the effects of TSLP on the production of angiogenic and lymphangiogenic factors from HLMs and the expression of intratumoral and peritumoral TSLP system (i.e., TSLP receptor and TSLP isoforms) in human lung cancer." (PMID 34440780, 2021). "Collectively, our results indicate that the TSLP system, widely expressed throughout the human mononuclear system, could be involved in chronic inflammatory disorders and lung cancer." (PMID 34440780, 2021). "The TSLP system, expressed in HLMs, MDMs, and monocytes, could play a role in chronic inflammatory disorders including lung cancer." (PMID 34440780, 2021).
lung carcinoma (continued). "However, a better comparison of the TSLP system should be performed among peripheral blood monocytes, MDMs and HLMs obtained from the same lung cancer patients." (PMID 34440780, 2021). "However, we identified the two TSLP isoforms in HLMs, MDMs and monocytes, and in human lung cancer tissue." (PMID 34440780, 2021). "In the present study, we have demonstrated that the TSLP system is constitutively expressed in macrophages purified from lung tissue of patients with lung cancer in monocyte-derived macrophages (MDMs) and in peripheral blood monocytes obtained from normal donors." (PMID 34440780, 2021). "Our results showing a synergistic interaction between IL-4 and LPS on the release of TSLP from human lung macrophages might have translational relevance in the context of lung cancer." (PMID 34440780, 2021). "Collectively, these results highlight a novel mechanism by which TSLP, produced by tumor and immune cells (e.g., macrophages), might amplify an immunosuppressive microenvironment in lung cancer." (PMID 34440780, 2021). "In vitro experiments showed STAT-1,−3, and−5 phosphorylation in TSLP-DCs that favored recruitment and differentiation of Tregs, possibly through CCL22 and TGFβ secretion, respectively, and in lung cancer patients the prevalence of Tregs correlated with TSLP expression in the tumor." (PMID 33042121, 2020). "In lung cancer tissue, increased levels of TSLP appear to be involved in the marked prevalence of immunosuppressive CD4+CD25+ Treg cells, which might help tumor cells escape the host immune system." (PMID 30214685, 2018). "We also examined the expression of the two TSLP isoforms (lfTSLP and sfTSLP), TSLPR, and IL-7Rα mRNAs in peritumoral and intratumoral lung cancer." (PMID 40873585, 2025). "Recently, we have found that TSLP, TSLPR, and IL-7Rα expression, examined by immunohistochemistry, was higher in the intratumoral lung cancer compared to the peritumoral area." (PMID 40873585, 2025). "TSLP, TSLPR, and IL-7Rα were overexpressed in intratumoral lung cancer. lfTSLP and sfTSLP were differently expressed in peritumoral and intratumoral lung cancer tissues." (PMID 40873585, 2025). "TSLP-activated CD4+ T helper 2 cells block early carcinogenesis by inducing terminal differentiation in spontaneous breast and lung cancer models." (PMID 36467403, 2022). "We evaluated the expression of TSLP, TSLPR, and IL-7Rα by immunohistochemistry in peritumoral and intratumoral areas of human lung cancer." (PMID 34440780, 2021). "The results of a typical experiment showed that the expression of TSLP, TSLPR and IL-7Rα was higher in the intratumoral area compared to peritumoral area of lung cancer." (PMID 34440780, 2021). "Our results provide evidence, to our knowledge for the first time, that TSLP isoforms, TSLPR, and IL-7Rα were expressed in both intratumoral and peritumoral lung cancer tissues." (PMID 34440780, 2021). "We found that chitin exposure rapidly induced the expression of three key type 2-promoting cytokines, IL-25, IL-33 and TSLP, in BEAS-2B transformed human bronchial epithelial cells and in A549 and H292 lung carcinoma cells." (PMID 27463381, 2016). "The number of Foxp3+ Tregs in lung cancer tissue was increased compared to non-cancer tissue, particularly in the group of TSLP+ cancers." (PMID 40873585, 2025). "TSLP expression, examined by immunohistochemistry, was increased in intratumoral lung cancer compared to non-cancer tissue and benign lesions." (PMID 40873585, 2025). "Incubation of HLMs with TSLP induced the release of TNF-α, VEGF-A, angiopoietin 2 and VEGF-C, indicating the role of TSLP system in lymphangiogenesis through a Th2-dependent pathway in lung cancer and other chronic inflammatory disorders." (PMID 38566083, 2024). "TSLP, TSLPR, and IL-7Rα were expressed in intratumoral and peritumoral areas of human lung cancer." (PMID 34440780, 2021).
lung carcinoma (continued). "TSLP, but not sfTSLP, can feedback on TSLPR on HLMs to induce the release of angiogenic factors that can contribute to lung cancer growth." (PMID 40873585, 2025).
melanoma (9 papers, 2018 to 2025). A malignant, usually aggressive tumor composed of atypical, neoplastic melanocytes. "Together, our data define a potentially novel pathway by which TSLP promotes melanoma growth and metastasis via regulation of the tumor-associated immunosuppressive microenvironment." (PMID 36107619, 2022). "Also, as DCs were not sufficiently represented in the available human cutaneous melanoma data sets, further studies will be required to investigate TSLPR-expressing DCs and their association with TSLP-induced GATA3+ Tregs in human melanoma." (PMID 36107619, 2022). "Melanoma in Braf/Pten mice is associated with induction of TSLP in epidermis." (PMID 36107619, 2022). "Our data suggest that targeting TSLP may constitute a new strategy to modulate the melanoma-associated immune microenvironment either alone or in combination with other therapeutic approaches." (PMID 36107619, 2022). "Melanoma cell-derived factors in Braf/Pten mice activated keratinocytes to release TSLP, which engaged TSLPR on DCs." (PMID 40873585, 2025). "This study highlights the role of TSLP in programming a protumoral immune microenvironment in melanoma." (PMID 40873585, 2025). "Yao and collaborators used genetically engineered models of melanoma and tumor cell grafting combined with TSLP knockout or overexpression, to identify a crosstalk between keratinocytes, immune cells, and melanoma cells in TME." (PMID 40873585, 2025). "Keratinocyte-derived TSLP promoted growth and metastasis of melanoma programming a suppressive tumor microenvironment." (PMID 40873585, 2025). "Keratinocyte-derived thymic stromal lymphopoietin (TSLP) can also suppress cytotoxic T-cells to promote the growth and metastasis of melanoma by promoting GATA binding protein 3 (GATA3) expressing Tregs." (PMID 40872475, 2025). "The study revealed that TSLP produced by keratinocytes in response to signals from melanoma cells promoted melanoma progression and metastasis through its actions on immune cells." (PMID 38775220, 2024). "Keratinocyte-derived TSLP is induced by signals from melanoma tumor cells and subsequently acts through immune cells to promote melanoma growth, progression, and metastasis." (PMID 36107619, 2022). "ELISA measurement showed that TSLP protein levels were elevated in B16F10-grafted WT or NSG ears in presence of melanomas (D35 for WT and D28 for NSG mice)." (PMID 36107619, 2022). "To address the role of TSLP in melanoma, we generated Braf/Pten mice in the Tslp–/– background (named Braf/Pten/Tslp–/–) by breeding the Tyr:Cre-ERT2BrafLSL–V600E/+Ptenlox/lox mice with Tslp–/– mice." (PMID 36107619, 2022). "Ear and dorsal melanoma lesions from Braf/Pten mice were taken at different times, and TSLP protein levels were measured by ELISA." (PMID 36107619, 2022). "In Braf/Pten melanoma-draining LNs, TSLP promoted not only GATA3+ Th2 cells, but also GATA3+ Tregs expressing a specific signature including ST2, CCR8, ICOS, PD-1, CTLA-4, OX40, and IL-10 — but not Th2 cytokines IL-4 and IL-13." (PMID 36107619, 2022). "Here, we report a protumoral role of TSLP derived from epidermal keratinocytes in driving the growth and metastasis of melanoma." (PMID 36107619, 2022). "Using genetically engineered models of melanoma and tumor cell grafting combined with TSLP-KO or overexpression, we defined a crosstalk between melanoma cells, keratinocytes, and immune cells in establishing a tumor-promoting microenvironment." (PMID 36107619, 2022). "Taken together, these results indicate that activation of TSLP expression in the epidermis promoted growth of Braf melanoma and accelerated the progression and metastasis of Braf/Pten melanoma." (PMID 36107619, 2022). "Keratinocyte-derived TSLP is induced by signals derived from melanoma cells and subsequently acts via immune cells to promote melanoma progression and metastasis." (PMID 36107619, 2022).
melanoma (continued). "Using these melanoma models, we found that TSLP expression was induced in the epidermis concomitantly with tumorigenesis." (PMID 36107619, 2022). "Lastly, it will be important to determine how melanoma cells signal to induce keratinocyte TSLP expression." (PMID 36107619, 2022). "Using mouse melanoma models or intradermal melanoma cell grafting combined with the ablation or overexpression of TSLP, we revealed a crosstalk between melanoma cells, keratinocytes, and immune cells in establishing a tumor promoting microenvironment." (PMID 36107619, 2022). "Taken together, these data indicate that genetic TSLP ablation slowed the growth and metastasis of melanoma in Braf/Pten mice." (PMID 36107619, 2022). "Moreover, GATA3+ Tregs were found enriched in invasive primary melanoma, suggesting similar TSLP-driven immunosuppressive mechanisms in human melanomas." (PMID 39201498, 2024). "Importantly, the examination of human cutaneous primary melanoma biopsies by IHC showed TSLP expression in epidermal suprabasal layers overlying invasive melanomas without a clear association between TSLP signals and Breslow depth." (PMID 39201498, 2024). "The genetic ablation of TSLP in this background delays melanoma growth and metastasis." (PMID 39201498, 2024). "Therefore, this study identified TSLP as a keratinocyte-derived factor promoting melanoma progression through the remodeling of its ecosystem toward an immunosuppressive environment." (PMID 39201498, 2024). "Thus, human melanoma cells, analogous to mouse melanoma cells, can possibly signal to keratinocyte to induce TSLP production in a conserved species cross-reactive manner." (PMID 36107619, 2022). "TSLP-dependent accumulation of GATA3+ Tregs in melanoma tumor sites." (PMID 36107619, 2022). "We previously showed that MC903 induces TSLP expression in epidermal keratinocytes in a dose-dependent manner, providing an opportunity to test whether melanoma growth could be promoted dose dependently by TSLP." (PMID 36107619, 2022). "TSLP promotes growth of oncogenic Braf-driven melanoma and accelerates their metastasis." (PMID 36107619, 2022). "We further examined whether melanoma metastasis to draining LNs was also promoted by MC903-induced TSLP expression." (PMID 36107619, 2022). "Genetic ablation of TSLP delays melanoma growth and metastasis." (PMID 36107619, 2022). "Genetic ablation of TSLP reduces GATA3+ Tregs in LNs draining Braf/Pten melanoma." (PMID 36107619, 2022). "Interestingly, i.d. grafting of human melanoma Lu1205 cells into NSG mouse ears induced the expression of mouse TSLP in the epidermis." (PMID 36107619, 2022). "TSLP promotes growth of skin-grafted B16F10 melanoma cells through immune cells." (PMID 36107619, 2022). "We next asked whether TSLP promoted melanoma growth by acting directly on melanoma cells or through immune cells." (PMID 36107619, 2022). "Braf/Pten melanoma cell growth was, thus, accelerated by TSLP in a dose-dependent manner." (PMID 36107619, 2022). "On the other hand, we investigated whether TSLP was induced by signals derived from melanoma cells or from immune cells." (PMID 36107619, 2022). "Therefore, there was a statistically significant increase in the percentage of TSLP-expressing samples in invasive melanoma compared with in situ melanoma." (PMID 36107619, 2022). "By combining genetic TSLP ablation with its drug-induced expression in Braf/Pten or Braf mice, we showed that TSLP promotes melanoma progression and mediates an important crosstalk between melanoma cells, keratinocytes, and immune cells in establishing the melanoma TME." (PMID 36107619, 2022). "Collectively, these results highlight a novel circuit involving keratinocytes-derived TSLP, which activates DCs and CD4+ cells to release IL-4 and IL-13, promoting the growth and metastasis of melanoma." (PMID 40873585, 2025).
melanoma (continued). "In contrast, the pharmacological induction of TSLP in epidermal keratinocytes promotes the formation and growth of BRAF melanoma, which normally develops slowly and accelerates the progression and metastasis of BRAF/PTEN melanoma." (PMID 39201498, 2024). "Importantly, the acceleration of pigmentated lesion formation and melanoma cell growth by MC903 was abolished in Braf/Tslp–/– mice, indicating that these effects were mediated through TSLP." (PMID 36107619, 2022). "TSLP induction in epidermal keratinocytes by engrafted B16F10 melanomas did not, therefore, appear to require the immune cells that are absent in NSG mice." (PMID 36107619, 2022). "TSLP was detected neither in melanoma cells nor in the dermis." (PMID 39201498, 2024). "In addition, we identified a potentially novel role for TSLP, via TSLP receptor (TSLPR) expressed by DCs, in promoting a subset of GATA3-expressing Tregs, and we uncovered a potentially new facet to how TSLP regulates melanoma progression through programming TME." (PMID 36107619, 2022).